PCM1 (pericentriolar material 1)
Description:
Required for centrosome assembly and function. Essential for the correct localization of several centrosomal proteins including CEP250, CETN3, PCNT and NEK2. Required to anchor microtubules to the centrosome. Also involved in cilium biogenesis by recruiting the BBSome, a ciliary protein complex involved in cilium biogenesis, to the centriolar satellites. Recruits the tubulin polyglutamylase complex (TPGC) to centriolar satellites.
Synonyms: PTC4; RET/PCM-1
Tractability: PROTAC: UniProt records ubiquitination sites on it; ubiquitination databases record sites on it; its protein half-life has been measured.
Gene: Protein-coding gene on chromosome 8 (17,922,746 to 18,029,996, forward strand). Ensembl gene ENSG00000078674.
Subcellular location: Cytoplasm, cytoskeleton; Cytoplasm, cytoskeleton, microtubule organizing center, centrosome; Cytoplasmic granule; Cytoplasm, cytoskeleton, microtubule organizing center, centrosome, centriolar satellite; Cytoplasm, cytoskeleton, cilium basal body
Subcellular location (Human Protein Atlas): Basal body; Centriolar satellite; Microtubules; Primary cilium; Cytosol
Pathways (Reactome):
Cell Cycle: AURKA Activation by TPX2; Loss of Nlp from mitotic centrosomes; Loss of proteins required for interphase microtubule organization from the centrosome; Recruitment of NuMA to mitotic centrosomes; Recruitment of mitotic centrosome proteins and complexes; Regulation of PLK1 Activity at G2/M Transition
Organelle biogenesis and maintenance: Anchoring of the basal body to the plasma membrane
Gene Ontology:
Molecular function: protein binding; protein-macromolecule adaptor activity; identical protein binding; molecular adaptor activity
Biological process: centrosome cycle; cilium assembly; cytoplasmic microtubule organization; intraciliary transport involved in cilium assembly; non-motile cilium assembly; positive regulation of intracellular protein transport; protein localization to centrosome; protein-containing complex localization to centriolar satellite; interkinetic nuclear migration; microtubule anchoring; microtubule anchoring at centrosome; negative regulation of neurogenesis
Cellular component: centriolar satellite; centrosome; ciliary basal body; ciliary transition zone; membrane; non-motile cilium; protein-containing complex; cytoplasm; cytosol; pericentriolar material; apical part of cell; centriole; cytoskeleton
Genetic constraint (gnomAD): Loss-of-function variants: 72 observed, 125.23 expected, observed/expected ratio (o/e) 0.57, 90% interval 0.47 to 0.7. The synonymous counts are far from expectation, so gnomAD's model fits this gene poorly and the ratio says little. Missense variants: 2,160 observed, 1,456.5 expected, observed/expected ratio (o/e) 1.48, 90% interval 1.43 to 1.54. Synonymous variants: 692 observed, 503.46 expected, observed/expected ratio (o/e) 1.37, 90% interval 1.29 to 1.46.
Homologues: Orthologues: chimpanzee PCM1 (99% identical), macaque PCM1 (97% identical), dog PCM1 (92% identical), rabbit PCM1 (92% identical), pig PCM1 (91% identical), guinea pig PCM1 (89% identical), mouse Pcm1 (89% identical), rat Pcm1 (89% identical), tropical clawed frog pcm1 (59% identical), zebrafish pcm1 (51% identical).
Diseases named in the same sentence as PCM1 in open-access papers:
PCM1 is named in the same sentence as 80 diseases in open-access papers, as found by Europe PMC text mining. Sharing a sentence is not in itself a finding about the gene and the disease. The quoted sentences say what the papers report.
ciliopathy (9 papers, 2010 to 2025). A genetic disorder of the cellular cilia or the cilia anchoring structures, the basal bodies, or of ciliary function. "SDCCAG8 was identified as a syndromic ciliopathy-associated gene in 2010, and was further proven to be a satellite protein due to its colocalization and interaction with PCM1." (PMID 40801568, 2025). "This includes Bbs4, an essential component of primary cilia that causes a ciliopathy (Bardet-Biedl syndrome) when disrupted, and PCM1 as shown here." (PMID 20531939, 2010). "Pcm1-null mice exhibit syndromic ciliopathies that manifest by renal degeneration and male infertility and are characterized by sperm immobility and defects in spermiogenesis." (PMID 40801568, 2025). "Pcm1-null and Sdccag8mut/mut mice share similar phenotypes in syndromic ciliopathy and male infertility, including renal degeneration, perinatal lethality, a reduced sperm number, sperm immobility, an abnormal head morphology and spermiogenesis defects." (PMID 40801568, 2025). "As a scaffold protein for the assembly and maintenance of centriolar satellites, pericentriolar material 1 (PCM1) is essential for proper ciliogenesis and ciliary functions, and Pcm1 knockout mice display ciliopathy-associated phenotypes such as dwarfism, hydronephrosis, and male infertility." (PMID 37466224, 2023). "Co-immunoprecipitation experiments demonstrated that CCDC66 interacts with numerous proteins that function in ciliogenesis (i.e. CEP72, CEP290 and PCM1) and CEP290 has also been previously implicated in retinal degeneration in human ciliopathies and mouse models." (PMID 33273526, 2020). "Several ciliopathy-associated proteins, including Bardel Biedl syndrome 4 (BBS4), CEP290, pericentriolar material 1 (PCM1), and orofaciodigital syndrome 1 (OFD1), localize to centriolar satellites and are critical for cargos entry and/or exit from the primary cilium." (PMID 32258032, 2020). "As mammalian PCM1 is particularly required for cilia function in ependymal cells and sperm, differential requirements for centriolar satellite function may be one determinant of tissue specificity in human ciliopathies." (PMID 36790165, 2023). "While background differences may influence penetrance and expressivity, it is possible that the absence of reported hydrocephaly and other ciliopathy-related phenotypes indicates that the Pcm1 gene trap allele is hypomorphic." (PMID 36790165, 2023). "Because retinal degeneration is characteristic of several ciliopathies and PCM1 was strongly expressed in the retina, we examined the retinas of Pcm1−/− mice using fundal imaging and histological analysis at 1 year of age." (PMID 36790165, 2023). "In addition, PCM-1 and FOR20 have no known linkage with ciliopathy, but are required for ciliogenesis." (PMID 23110211, 2012).
schizophrenia (8 papers, 2007 to 2024). A major psychotic disorder characterized by abnormalities in the perception or expression of reality. "Sequencing of PCM1 in human cohorts and zebrafish in vivo complementation suggests PCM1 mutations can contribute to schizophrenia." (PMID 33214552, 2020). "Consistently, mutations in PCM1 were associated with schizophrenia 75, 76, 77, and PCM1, Hook3, DISC1, and SDCCAG8 were implicated in maintaining neural progenitor cells and neuronal migration during cortical development." (PMID 31023719, 2019). "Firstly, the interaction of the schizophrenia candidate gene PCM1 and HAP1, huntingtin-associated protein 1, has been confirmed." (PMID 21298101, 2011). "Moreover, DISC1 and BBS4 have been shown to be required to PCM1 localization as well and are synergistically associated with mental pathologies, such as schizophrenia." (PMID 38961488, 2024). "However, psychotic schizophrenia-like symptoms have also been noted amongst Huntington's disease patients consistent with the interaction of huntingtin with proteins from other schizophrenia-associated genes such as PCM1, PDE4B and DPYSL2." (PMID 21298101, 2011). "Our data emphasize a role for the pericentriolar material in the postnatal brain, with progressive degenerative ciliary and behavioral phenotypes; and they support a contributory role for PCM1 in some individuals diagnosed with schizophrenia." (PMID 33214552, 2020). "Ultra-rare missense mutations in patients with schizophrenia have been reported for APP PCM1, and indeed DISC1." (PMID 21195721, 2012). "Disrupted in schizophrenia 1 (Disc1), pericentriolar material 1 (PCM-1), and human jouberin (Abelson helper integration site 1 (AHI1)) are linked with schizophrenia, hamartin (Tuberous sclerosis 1 (TSC1)) is linked with autism, and pericentrin (PCNT), DCDC2, and Dyx1c1 are linked with dyslexia." (PMID 28125008, 2017). "Furthermore, emerging evidence of genetic association (NDEL1, PCM1, PDE4B) and copy number variation (NDE1) implicate several DISC1-binding partners as risk factors for schizophrenia in their own right." (PMID 21195721, 2012). "Finally, we sequence PCM1 in two human cohorts with severe schizophrenia." (PMID 33214552, 2020). "However, although PCM-1 and AHI1 are associated with schizophrenia, there are no observations of implication of either Plk1 or Rab8, into pathogenesis of schizophrenia." (PMID 28125008, 2017).
eosinophilia (6 papers, 2021 to 2026). "This case report presents a rare clinical manifestation of a myeloid/lymphoid neoplasm with eosinophilia (MLN-eo) with PCM1::JAK2 rearrangement that initially presented as B-cell acute lymphoblastic leukaemia (B-ALL)." (PMID 41530508, 2026). "Both the World Health Organization (WHO) and the International Consensus Classification (ICC) have updated the former category of “Myeloid/Lymphoid Neoplasms Associated with Eosinophilia and Rearrangement of PDGFRA, PDGFRB, FGFR1, or PCM1::JAK2”." (PMID 41530508, 2026). "The PCM1-JAK2 fusion (PCM1 exon 25-JAK2 exon 9) may be expressed in MPN, MDS B-ALL, or AML, and has been associated with different levels of eosinophilia in both blood and BM." (PMID 33418988, 2021). "If either PDGFRA, PDGFRB, FGFR1, or JAK2::PCM1 gene rearrangement is identified, the diagnosis should be classified as “myeloid or lymphoid neoplasms with eosinophilia and tyrosine kinase gene fusions”; eosinophilia may be a clue to this alternative diagnosis." (PMID 38067330, 2023). "In patients with PCM1:JAK2, the bone marrow is typically hypercellular demonstrating eosinophilia, erythroid hyperplasia with dyserythropoiesis, and myelofibrosis." (PMID 38611061, 2024). "After ruling out the hypothesis of non−hematologic origin, testing for gene rearrangements associated with clonal eosinophilia, such as BCR::ABL1, PDGFRA, PDGFRB, FGFR1, PCM1::JAK2, and JAK2::V617F, did not yield any definitive clues." (PMID 38992589, 2024).
leukemia (6 papers, 2016 to 2026). A malignant (clonal) hematologic disorder, involving hematopoietic stem cells and characterized by the presence of primitive or atypical myeloid or lymphoid cells in the bone marrow and the blood. "PCM1 codes for a protein that is responsible for anchoring microtubules to centrosomes and has previously been associated with thyroid cancer, leukemia, and T-cell lymphoma." (PMID 31053132, 2019). "In particular, JAK2 fusion partners have been identified alongside PCM1 — including BCR and ETV6— in both B- and T-lineage leukemias, further complicating diagnostic classification and therapeutic decision-making." (PMID 41530508, 2026). "In addition, activating JAK2 gene fusions with the TEL (ETV6) (TEL-JAK2) and PCM1 genes has been identified in leukemia patients." (PMID 27752371, 2016). "In contrast, CUL4A, a core component of a cullin-based E3 ubiquitin ligase complex and overexpressed in cancer, and PCM1, a centrosome binding protein translocated to the JAK2 locus in certain leukemias, both bound uniquely in α7HMZ colons." (PMID 27166517, 2016). "Finally, the detection of both NUP214::ABL1 and PCM1::FGFR1 fusions in the near ETP-ALL of case 8 leaves no information as to which fusion was the primary and which was secondary in this leukemia." (PMID 38571499, 2024).
chronic myeloid leukemia (5 papers, 2015 to 2025). "PCM1 was also altered which is associated with papillary thyroid carcinomas and a variety of hematological malignancies, including atypical chronic myeloid leukemia and T-cell lymphoma." (PMID 31105870, 2019). "For cladribine, SAMHD1 involved in proliferation of acute myeloid leukemia cells and PCM1 involved in gene fusions in atypical chronic myeloid leukemia were found." (PMID 41146244, 2025). "These potentially include patients with fusions of JAK2 with PCM1, ETV6 and BCR, T-cell large granular lymphocytic leukaemia, chronic lympho-proliferative disorders of natural killer cells, Waldenstrom’s Macroglobulinaemia, chronic myeloid leukaemia and chronic lymphocytic leukaemia." (PMID 26131691, 2015).
glioblastoma (4 papers, 2019 to 2024). The most malignant astrocytic tumor (WHO grade IV). "In support of this notion, it has been recently reported that dysfunction of primary cilia by loss of ciliary proteins such as PCM1 and Tctn3 increases apoptotic cell death in glioblastoma or caused neuronal apoptosis in mice." (PMID 31844040, 2019). "Dysfunction of the primary cilia, due to the loss of ciliary proteins like PCM1 (Pericentriolar Material 1) and TCTN3 (Tectonic Family Member 3), has been linked to increased apoptotic cell death in glioblastoma and neuronal cells in mice." (PMID 39201546, 2024). "For instance, PCM1-mediated depletion of cilia in patient-derived glioblastoma cell lines led to decreased proliferation and increased sensitivity to temozolomide (TMZ) treatment." (PMID 38188300, 2023). "For comparison, the U-87MG cell line represents glioblastoma hypodiploid cells derived from a primary brain tumor and carries several mutations (i.e., CDKN2A, RAS, PTEN, HF1 and PCM1)." (PMID 31195298, 2019).
Bardet-Biedl syndrome (3 papers, 2010 to 2023). A ciliopathy with multisystem involvement. "PCM1 depletion has been shown to lead to loss of primary cilia and PCM1 interaction with CEP290 and Bardet-Biedl Syndrome (BBS) proteins are required for ciliogenesis." (PMID 37256063, 2023).
breast carcinoma (3 papers, 2017 to 2023). "The parental gene of novel_circ_0006360 is PCM1, a key gene in both mammary gland development and breast cancer, which is related to cell proliferation and the cell cycle." (PMID 36425117, 2022). "The protein abundance of PCM1 was indeed elevated in breast cancer and correlated with that of USP9X." (PMID 28361952, 2017). "Interestingly, we observed significantly elevated levels of PCM1 and CEP290, but not others in DNAJA2-deficient mouse breast cancer cell line 4T1 and HeLa cells." (PMID 37640708, 2023).
glioma (3 papers, 2014 to 2025). A benign or malignant brain and spinal cord tumor that arises from glial cells (astrocytes, oligodendrocytes, ependymal cells). "After single or repeated TTFields exposure, we plated cells in serum for 4 days, fixed, and immunostained for ARL13B alone or combined with pericentriolar material 1 (PCM1), another protein that clusters around the basal body and centrioles in glioma cells, or OFD1." (PMID 35359402, 2022). "Previously, we found that deleting key ciliogenesis genes (e.g., PCM1, KIF3A) enhanced sensitivity of glioma cells to TMZ." (PMID 35359402, 2022). "PCM1 has significant aCGH/expression correlation in the breast, myeloma, lymphoma, prostate, urothelial, lung, pancreatic and neuroblastoma data sets but not in oesophageal, mesothelioma or gastric (and not annotated in glioma)." (PMID 25148247, 2014).
T-cell lymphoma (3 papers, 2019 to 2026). "However, PCM1::JAK2 fusion is rarely observed in other lymphoproliferative malignancies (such as T-cell lymphomas)." (PMID 41530508, 2026).
acute lymphoblastic leukemia (2 papers, 2013 to 2026). Leukemia with an acute onset, characterized by the presence of lymphoblasts in the bone marrow and the peripheral blood. "Among these, gene rearrangements involving PCM1::JAK2 are rare and may present diagnostic challenges, particularly when manifesting as acute lymphoblastic leukemia (ALL)." (PMID 41530508, 2026). "Mutation of JAK2 is observed in several hematological disorders including ET, Polycythemia Vera, Primary Myelofibrosis and Acute Lymphoid Leukemia (ALL) as well as chromosomal translocations involving the fusion partners TEL, BCR, PCM1, PAX5, SEC 31A and SSBP2." (PMID 24086539, 2013).
cervical carcinoma (2 papers, 2020 to 2021). A carcinoma arising from either the exocervical squamous epithelium or the endocervical glandular epithelium. "Analogous to GFP-PCM1 and endogenous PCM1, GFP-PCM1-FKBP localized to satellites in transfected human cervical carcinoma (HeLa) cells without altering their distribution." (PMID 32555591, 2020).
hydronephrosis (2 papers, 2023). Collection of urine in the renal pelvis that results in dilatation of the renal pelvis and calyces. "In addition, Pcm1−/− mice exhibited cerebellar hypoplasia and partially penetrant hydronephrosis, both of which can be caused by defective Hedgehog signaling, a signal transduction pathway dependent on cilia." (PMID 36790165, 2023). "A proportion of viable Pcm1−/− mice (n = 2/15) developed hydronephrosis, which can also result from attenuated Hedgehog signaling." (PMID 36790165, 2023). "Pcm1−/− mice display partially penetrant perinatal lethality with survivors exhibiting hydrocephalus, oligospermia, and cerebellar hypoplasia, and variably expressive phenotypes such as hydronephrosis." (PMID 36790165, 2023).
liver cancer (2 papers, 2017 to 2023). An epithelial or non-epithelial malignant neoplasm that arises from the liver. "PCM1 includes genes related to cell cycle activity and liver cancer development." (PMID 36829466, 2023). "and cancer driver genes (ATRX, MDC1, RIF1, APC and PCM1) showed a phosphorylation related signal transition network affecting cell proliferation ability and revealed the extreme complex nature of phosphoproteome transformation in liver cancer cells." (PMID 28883432, 2017). "In order to evaluate the activation of HCC-related molecular mechanisms in PCM1 classified groups, we performed GSEA analysis for curated liver-cancer-related gene sets from the MsigDB database in GSE83148 and GSE84044." (PMID 36829466, 2023). "As enrichment of liver-cancer-related gene sets suggested that a subset of PCM1 genes may also have roles in HCC tumorigenesis, we compared the expression of PCM1 genes between HCC tumors and normal liver." (PMID 36829466, 2023). "The analysis of the immunohistochemical stainings validated that proteins coded by a group of PCM1 genes were overexpressed in liver cancer, while minimal or no expression was detected in normal liver." (PMID 36829466, 2023).
lymphoid neoplasm (2 papers, 2023 to 2024). A neoplasm composed of a lymphocytic cell population which is usually malignant (clonal) by molecular genetic and/or immunophenotypic analysis. "The PCM1 gene as partner in the chimera PCM1::JAK2 has been implicated in the pathogenesis of also other acute myeloid/lymphoid neoplasms whereas rearrangements of FGFR1 are rare." (PMID 38571499, 2024).
male infertility (2 papers, 2023 to 2025). The inability of the male to effect fertilization of an ovum after a specified period of unprotected intercourse. "Several satellite genes have been associated with male infertility and sperm flagellum defects in humans and mice, including PCM1, CEP131, BBS4, OFD1, CEP290, CCDC13, etc.." (PMID 40801568, 2025). "Pcm1−/− and Sdccag8mut/mut mice shared similar phenotypes in sperm flagellar defects and male infertility, which prompted us to investigate the potential functional association between those two proteins in flagellum biogenesis." (PMID 40801568, 2025). "In the Sdccag8mut/mut spermatid, lacking this region led to the instability of PCM1 and mislocalization of the satellite-associated proteins, CEP131, and BBS4, which could be attributed to observed male infertility, as CEP131 and BBS4 are essential for flagellum biogenesis and male fertility." (PMID 40801568, 2025).
neuroblastoma (2 papers, 2014 to 2016). Neuroblastoma (NB) is the most common solid, extracranial childhood tumor. "To test this hypothesis, we generated two small hairpin RNA (shRNA) vectors that expressed shRNAs that targeted mouse PCM1 and validated the efficiency of these shRNAs in knocking down PCM1 in mouse neuroblastoma (N2A) cells." (PMID 26883496, 2016).